PAK1 (p21 (RAC1) activated kinase 1)
Diseases named in the same sentence as PAK1 in open-access papers (continued):
Sharing a sentence is not in itself a finding about the gene and the disease.
breast carcinoma (continued). "Other than upregulating PAK1, hyperactivity of small GTPases Rac3 was found to augment the kinase activity of PAK1 in breast cancer." (PMID 25093037, 2014). "In breast cancer, PAK1 expression and activity was increased and correlated with a more malignant phenotype." (PMID 25182632, 2014). "PAK1 phosphorylates and induces the transactivation function of ER-α, and such activation is believed to promote hormone independence in breast cancer cells." (PMID 25093037, 2014). "In other studies, PAK1 genomic amplification found at 11q13 was prevalent in luminal breast cancer and breast cancer cells." (PMID 25182632, 2014). "There is evidence that many tumours, including breast cancers, are addicted to abnormal activation of PAK1, a Ser/Thr kinase which in turn stimulates cyclin D1, for their growth." (PMID 25026295, 2014). "Studies showed that miR-7 has an inverse correlation with Pak1 expression in human breast cancer cells." (PMID 23202960, 2012). "Among these, growth factor stimulation causes phosphorylation at Ser25 and Ser38, although phosphorylation at Ser38 alone is dependent on Pak1 in breast cancer cells." (PMID 22315597, 2012). "Taken together, our identification of PAK1 as an “Achilles’ heel” for a subpopulation of breast cancer provides evidence of oncogene addiction and a rationale for PAK1-directed therapy in this disease indication." (PMID 21653999, 2011). "In luminal breast cancer, the expression and localization of PAK1 protein was recently assessed in primary tumors from 403 premenopausal patients that were randomized to two years of adjuvant tamoxifen or no treatment." (PMID 21653999, 2011). "Increased PAK1 expression and activity in breast tumor is well documented, whereas inhibition of PAK1 activity in breast cancer cells leads to suppression of motile phenotypes as well as invasiveness of these cells." (PMID 23554696, 2011). "PAK1 genomic copy number and protein expression level were also ascertained in 216 and 274 human breast carcinoma samples, respectively." (PMID 21653999, 2011). "PAK1 phosphorylates an alternate, but in breast cancer frequently present, isoform of the SRC3 steroid-receptor cofactor (SRC3-3δ4), allowing it to bridge between EGF-R and FAK1 (focal adhesion kinase 1) and thereby activating ERK1/2 MAPK." (PMID 22295213, 2011). "A pull-down reagent comprised of the Pak1-RBD was used as an affinity probe in immunohistochemistry experiments to demonstrate Rac activation in FFPE fixed mouse mammary tumors driven by Neu and TGFβ1." (PMID 21358804, 2011). "Taken together, this study identifies a PI3K/PAK1/ERK signaling pathway for LPA-stimulated breast cancer cell migration." (PMID 21209852, 2010). "LPA treatment can lead to the activation of the PI3K/PAK1/ERK cascade in breast cancer cells and contribute to breast cancer migration." (PMID 21209852, 2010). "We found that Pak1 over-expressing luminal breast cancer cell lines are significantly more sensitive to Mek inhibition compared to those that express Pak1 at low levels." (PMID 19317917, 2009). "Pak1 also phosphorylates T261 of ErbB3 binding protein 1 (Ebp1), a transcriptional co-repressor that inhibits the growth of breast cancer cells." (PMID 19557173, 2009). "Through an analysis of our breast cancer network models, we identified Pak1 as a putative differential regulator of the MAPK cascade in our cell lines." (PMID 19317917, 2009). "For example, PAK1/2 activity is elevated in the heterozygous tumors, and PAK1 hyperactivation promotes mammary tumor formation in part by activating p38MAPK signaling and proliferation." (PMID 19703301, 2009). "In light of the potential role of both PAK1 and Ebp1 in breast cancer progression and their activation by HRG, we determined if Ebp1 was a substrate for PAK1." (PMID 18283314, 2008).
breast carcinoma (continued). "The p21-activated serine/threonine kinase 1 (PAK1), which plays an important role in breast cancer progression and resistance to the anti-oestrogen tamoxifen, is also activated by HRG." (PMID 18283314, 2008). "Both HRG treatment and expression of a constitutively activated PAK1 in MCF-7 breast cancer cells enhanced threonine phosphorylation of Ebp1." (PMID 18283314, 2008). "Known PAK1 effectors in breast cancer pathogenesis include proteins involved in actin reorganisation, metabolic regulation, apoptosis, differentiation and transcriptional regulation." (PMID 18283314, 2008). "Our findings suggest that the phosphorylation and inactivation of Ebp1 by PAK1, with subsequent abrogation of Ebp1's growth inhibitory effects, is a new mechanism whereby PAK1 induces growth of breast cancer cells." (PMID 18283314, 2008). "Activation of PAK1 results in actin phosphorylation in breast cancer cells, leading to a reorganisation of the cytoskeleton that favours cell migration and invasiveness." (PMID 18283314, 2008). "Similarly, breast cancer displayed a significant enrichment of PAK1 alterations (10%), with other PAKs showing ≤3% alterations." (PMID 39756822, 2025). "We hypothesized that VEGFD and PAK1 may play pivotal roles in the F. nucleatum‐promoted proliferation and migration of breast cancer cells." (PMID 40070022, 2025). "Elevated PAK1 kinase activity correlates with an invasive phenotype in breast cancer cells." (PMID 40070022, 2025). "We inoculated human breast cancer TMX-28 cells (a variant of the MCF-7 breast cancer cells(Fasco, Amin, Pentecost, Yang, & Gierthy, 2003), stably overexpressing GFP, PAK1 WT or PAK1 Y3F (the clones were characterized previously in) into the mammary pads of NSG mice." (PMID 38660565, 2024). "Since our data indicate that macropinocytosis is required for ECM endocytosis in breast cancer cells, we wanted to investigate whether PAK1-mediated ECM uptake was required for ECM-dependent cell growth." (PMID 38227562, 2024). "PAK1 is a serine/threonine kinase gene overexpressed in some human breast carcinomas with poor prognosis, and aberrant PAK1 expression is an early event in the development of some breast cancers." (PMID 38609844, 2024). "Here we first show that PRL-activated pTyr-PAK1 enhances breast cancer growthin vivo." (PMID 38660565, 2024). "Since we have previously shown that PAK1, in response to PRL, increases the breast cancer cells migration and invasionin vitro; reviewed in and) as well as metastasisin vivo, we focused the present study on the role of pTyr-PAK1 in regulation of EMT." (PMID 38660565, 2024). "Although these observations suggest that PAK1 has a role in breast cancer, its precise role in breast cancer progression remains unknown." (PMID 38933712, 2024). "PAK1 is upregulated in various cancers, including pancreatic cancer, breast cancer and HCC." (PMID 37537668, 2023). "PAK1 is overexpressed in breast cancer and hence is identified as an oncogene." (PMID 37943025, 2023). "Pak1 expression in breast cancer positively correlates to metastasis and poor prognosis." (PMID 37258566, 2023). "In addition, miR-142-3p served as a tumor suppressor by regulation of RAC1/PAK1 signaling in breast cancer." (PMID 37403081, 2023). "The cytoplasmic levels of PAK1 correlated with recurrence rate and mortality in breast cancer." (PMID 37190165, 2023). "In breast cancer cells, prolactin-induced PAK1 activation results in augmented cell motility." (PMID 37190165, 2023). "Whereas overexpression of PAK1 was identified as an independent prognostic marker of poor outcomes in ovarian cancer, it is a nuclear expression and phosphorylation (Ser305) in breast cancer cells that predict resistance to tamoxifen therapy." (PMID 37190165, 2023).
breast carcinoma (continued). "The phosphorylation of EBP1 or CtBP by PAK1 induces tamoxifen resistance in breast cancer." (PMID 36230657, 2022). "In addition, ivermectin inhibits the AKT/mTOR signaling pathway through the ubiquitinal degradation of PAK1, thereby promoting autophagy in breast cancer cells." (PMID 36230657, 2022). "In addition, PAK1 gene amplification or protein overexpression was also observed in many other kinds of tumors, including breast cancer, colorectal cancer, and hepatocellular carcinoma." (PMID 34307365, 2021). "In order to examine signaling proteins that might be regulated by Pak1 we used a phospho-antibody array, which contains several dozen of breast cancer-relevant phospho-protein specific antibodies." (PMID 35111748, 2021). "We found a strong correlation between Pak1 and CaMKII expression in human breast cancer samples, and combined inhibition of Pak1 and CaMKII with small-molecule inhibitors was synergistic and induced apoptosis more potently in Her2 positive and triple negative breast cancer (TNBC) cells." (PMID 35111748, 2021). "In this study, we identified CaMKII as a new Pak1 substrate in breast cancer cells." (PMID 35111748, 2021). "In addition, Pak1 and CaMKII are co-expressed in breast cancer cell lines and using a human breast cancer tissue microarray (TMA), we observed a significant correlation between the expression levels of these two kinases." (PMID 35111748, 2021). "Finally, we assessed whether Pak1 and CaMKIIγ expression is associated with breast cancer patient outcome by examining the expression level of both genes at mRNA level from a set of data of a breast cancer METABRIC study obtained from the Cancer Genome Atlas website." (PMID 35111748, 2021). "Indeed, recent studies have been shown that PAK1 inhibition impeded carcinogenesis in several tumors, such as breast cancer, intestinal tumor, lung cancer, and melanoma 37-39." (PMID 32863957, 2020). "This suggests that PAK-1 inhibition may be an effective strategy to overcome tamoxifen resistance in breast cancer." (PMID 33321758, 2020). "Furthermore, PAK1, a target gene of miR-494, functioned as an oncogenic factor in breast cancer via activating MAPK signaling pathway and remodeling cytoskeletal." (PMID 32190006, 2020). "PAK-1 (and other PAKs) are overexpressed in various cancers including prostate and breast cancers." (PMID 33321758, 2020). "Tubulin cofactor B (TCoB), which exhibits overexpression and hyperphosphorylation in breast cancer can be directly bound and phosphorylated on serine 65 and 128 by PAK1, and then interact with tubulin to regulate the polymerization of new microtubules and mitosis." (PMID 32863957, 2020). "Consequently, there has been significant interest in the identification of potent PAK1 inhibitors with novel scaffold that are capability of clinical development for the breast cancers treatment." (PMID 32752894, 2020). "PAK-1 is an attractive therapeutic target in various cancers including breast cancer." (PMID 33321758, 2020). "PAK1 silencing in breast cancer cells decreased mammosphere formation." (PMID 31658701, 2019). "We suspect that the PAK4 phosphorylation of ERα may take place in the cytoplasm, and this phosphorylation is weaker than the PAK1-mediated ERα-Ser305 phosphorylation in breast cancer." (PMID 30177834, 2019). "PAK1 inhibitor treatment reduced the proliferation of breast cancer cells." (PMID 31658701, 2019). "The Stat3/PAK1 complex is essential for IL-6 gene expression and breast cancer stemness." (PMID 31658701, 2019). "PAK1/Stat3 signaling regulates CSC formation, and PAK1 may be an important target for treating breast cancer." (PMID 31658701, 2019). "Based on these activities of AURKA and PAK1, we hypothesized that combined inhibition of both could have synergistic anti-tumor effects in breast cancer." (PMID 31254157, 2019).
breast carcinoma (continued). "Dual targeting of AURKA and PAK1 may be a promising therapeutic strategy for treatment of breast cancer, with a particular effectiveness in luminal and HER2-enriched tumor subtypes." (PMID 31254157, 2019). "Consistent with previous reports that PAK1 acted as an oncogene in breast cancer, PAK1 silencing significantly decreased the proliferation ability, colony formation ability and motility in MDA-231-LUC cells, which was similar to the phenotype induced by miR-494." (PMID 28055013, 2017). "Furthermore, PAK1, which acts as an oncogene in breast cancer by activating MAPK signal pathway and remolding cytoskeletal, is demonstrated to be a direct target gene of miR-494." (PMID 28055013, 2017). "Furthermore, re-expression of PAK1 partially reverses miR-494-mediated proliferative and clonogenic inhibition as well as migration and invasion suppression in breast cancer cells." (PMID 28055013, 2017). "Ectopic expression of activated Pak1 has been shown to induce mouse mammary tumors." (PMID 28391240, 2017). "Furthermore, we provide in vivo evidence that PRL-induced pTyr-PAK1 increases breast cancer cell metastasis." (PMID 27542844, 2016). "PAK1 confers resistance to the estrogen antagonist tamoxifen in breast cancer." (PMID 27713506, 2016). "Thus, our current data on pTyr-PAK1 regulation of FAK phosphorylation bring insight into the mechanism of PRL-stimulated motility of breast cancer cells." (PMID 27542844, 2016). "Finally, we demonstrate for the first time that tyrosyl phosphorylation of PAK1 by PRL increases breast cancer cell metastasis in vivo." (PMID 27542844, 2016). "Finally, our results of a TCGA analysis showed that PAK1 overexpression in human breast cancer specimens correlates with the expression of most FA/BRCA genes." (PMID 27740936, 2016). "Finally, the results of a TCGA analysis we performed showed that PAK1 overexpression in human breast cancer samples correlates with the expression of most FA/BRCA genes, particularly with FANCI." (PMID 27740936, 2016). "Additionally, PRL-induced pTyr-PAK1 is localized at small adhesion complexes at the cell periphery and regulates adhesion turnover in breast cancer cells, a process that is absolutely critical for cell motility." (PMID 27542844, 2016). "In breast cancer, regulation of Pak1 by estrogen has been reported." (PMID 26218748, 2015). "Thus, no consistent correlation was detected between the expression of PAK family members other than PAK4 (PAK1, 2, 3, 5, 6) and the patient outcome of endocrine treated breast cancer patients in the two databases." (PMID 26554417, 2015). "Given the evolutionarily conserved role of PAK1 in regulating cytoskeletal dynamics and the common use of microtubule inhibitors in later lines of breast cancer treatment, we evaluated the mechanism and potential therapeutic benefit of FRAX1036 combination with docetaxel." (PMID 25902869, 2015). "It was shown that PAK1 could upregulate cyclin D1 transcription in breast cancer cells thus fueling the cells with proliferative advantage." (PMID 25093037, 2014). "Inhibitors of PAK1, a downstream effector in the Ras pathway, have also been reported to suppress the growth of NF1-deficient MPNST cells as well as neurofibromin-deficient human breast cancer (MDA-MB-231) xenografts in mice." (PMID 25026295, 2014). "In breast cancer, the activity of PAK1 is upregulated by various mechanisms." (PMID 25093037, 2014). "Experimental manipulation also revealed that a constitutively active form of PAK1 could rapidly induce breast cancer cell proliferation and aggressive cell phenotypes, including anchorage-independent growth and mitotic defects." (PMID 25182632, 2014). "In addition, the subcellular localization of PAK1 staining is related to clinicopathologic tumor parameters in breast cancer." (PMID 25182632, 2014). "Furthermore, ABCA induces Cdc42 and PAK-1 signaling, which in turn are regulative for breast cancer ER/PR expression in vitro and in vivo." (PMID 23829168, 2013).
breast carcinoma (continued). "miR-7 has also been reported to target PAK1 in breast cancer cells." (PMID 22876288, 2012). "The idea that both Pak1 and Pak4 could have roles in breast cancer has very important implications in the future drug development." (PMID 23326684, 2012). "Thus, during breast cancer progression, there are increased levels of Pak1 protein while miR-7 expression levels and HoxD10 are both downregulated as the cancer becomes more invasive." (PMID 23202960, 2012). "Therefore, our results suggest that PAK1 activation serves as a mediator of EGF-stimulated breast cancer cell migration." (PMID 23554696, 2011). "In this study, we investigated whether Rac1/ROS regulates PI3K/Akt and PAK1 signaling and is critically linked to EGF-mediated breast cancer cell migration." (PMID 23554696, 2011). "This provides a novel turn to the role of PAK1 overexpression in breast cancer." (PMID 22295213, 2011). "We have also found that LPA can stimulate ROS generation in breast cancer cells, which may serve as an important mediator for LPA to stimulate breast cancer cell migration through the activation of PI3K/PAK1/ERK signaling pathway." (PMID 21209852, 2010). "Consequently, we conclude that PI3K is an upstream component of the PAK1/ERK signaling pathway in LPA-stimulated breast cancer cells." (PMID 21209852, 2010). "Moreover, an increase of Rac1 and Pak1 activity or overexpression have been observed in breast cancer tissues and metastatic lymph nodes." (PMID 20426825, 2010). "Mapping of sub-networks in the EGFR-MAPK pathway in different breast cancer cell lines reveals that PAK1 may be a marker for sensitivity to MEK inhibitors." (PMID 19317917, 2009). "Pak1 itself may aid breast cancer development by phosphorylating nuclear proteins, including estrogen receptor alpha." (PMID 19557173, 2009). "In addition, the dynein light chain, LC8, has been described to cooperate with Pak1 in malignant transformation of breast cancer cells." (PMID 19557173, 2009). "Forced expression of constitutively active Pak1 leads to increased proliferation and anchorage-independent growth of MCF-7 cells, a breast cancer cell line, whereas expression of a kinase dead Pak1 protein reduces the invasiveness of MDA-MB-435 breast cancer cells." (PMID 19557173, 2009). "Recent data indicate an important role for PAK1 in breast cancer progression." (PMID 18283314, 2008). "Our findings position PAK1 as a mediator of resistance to endocrine therapies suggesting that targeting PAK1 may present a novel strategy to overcome endocrine therapy resistance in ER+ breast cancer." (PMID 42249585, 2026). "Targeting PAK1 by ivermectin may open its use in other cancers, as PAK1 is needed for growth in more than 70% of human cancers, including pancreatic, colon, prostate, and neurofibromatosis tumors in addition to breast cancer." (PMID 38606261, 2024). "Moreover, Pak1 kinase increased activity correlated to invasive phenotype in breast cancer cells." (PMID 37258566, 2023). "Loss of PAK1 prolonged survival and showed loss of β-catenin in the MMTV-HER2 transgenic mice; when treated with small-molecule inhibitors of PAK or β-catenin, it showed tumor regression; and combined inhibition was synergistic in mice bearing xenografts of HER2-positive breast cancer cells." (PMID 33796531, 2021). "Furthermore, our results indicate that Pak1 and CaMKII expression is correlated in human breast cancer specimens, and our analysis of the METABRIC study showed significantly worse overall survival in breast cancer patients with co-expression of Pak1 and CaMKII." (PMID 35111748, 2021). "We showed that PAK1 inhibition reduced tumor cell migration in multiple types of cancer cells harboring p27 mislocalization, including fibrosarcoma, breast cancer, and renal carcinoma, suggesting that the cytoplasmic p27‐mediated PAK1 activation may be extended to other types of cancer." (PMID 31872963, 2020).